IL21 (interleukin 21)
Diseases named in the same sentence as IL21 in open-access papers (continued):
Sharing a sentence is not in itself a finding about the gene and the disease.
asthma (continued). "In this review, we summarize the recent progress regarding the role of TFH cells and their signature cytokine interleukin (IL)-21 in asthma from mouse studies and clinical reports." (PMID 31921177, 2019). "In this review, we have summarized recent discoveries related to the role of TFH cells and IL-21 in mouse models and patients with asthma." (PMID 31921177, 2019). "Consistently, an increased frequency of IL-21-expressing CD4+ T cells is also observed in asthma patients." (PMID 31921177, 2019). "In the OVA-induced asthma model, the administration of exogenous IL-21 reduced IgE production and decreased eosinophil recruitment into the airway." (PMID 31921177, 2019). "In our review of the research using animal models and human patient samples, TFH cell and its signature cytokine IL-21 were evidenced to be largely involved in asthma." (PMID 31921177, 2019). "IL-21 administration in an animal model of asthma reduces titres of antigen-specific IgE and IgG1 antibodies, as well as airway hyperresponsiveness and lung eosinophil recruitment." (PMID 18315837, 2008). "Some studies also found that probiotics could improve lung function and clinical symptoms for asthma patients, accompanied by a decrease of cytokines such as interleukin‐6 (IL‐6), IL‐17, and IL‐21." (PMID 39479674, 2024). "Additional research has demonstrated that IL-1β, IL-6, anti-IFN-γ, and IL-21, which is a cytokine environment that stimulates T cells in asthma to differentiate into the same biphenotypic cells, promote dual-positive TH2/TH17 cell differentiation, worsening asthma." (PMID 39439788, 2024). "Moreover, the indirect effects of MICB, PDE4D, and IL‐21 on childhood asthma via BMI are relatively modest, at 3.31%, 5.03%, and 3.43%, respectively." (PMID 38730525, 2024). "In human asthma, elevated IL-21 expression correlates with disease severity." (PMID 37932719, 2023). "Th17 cells produce IL-17A, IL-17F, IL-21, IL-22, and TNF-α to perform their functions, and IL-17A and IL-17F are linked to severe asthma with neutrophil inflammation and responsible for corticosteroid resistance in asthma." (PMID 38203353, 2023). "According to multiple research, children, and adults with obesity-associated asthma had higher peripheral blood levels of IL-17A, IL-21, and TNF-α than non-obese patients." (PMID 37377958, 2023). "Because IL-21 has a profound effect on IgE production, supplementation with IL-21 may rebalance the elevated IgE levels in patients with asthma." (PMID 34867940, 2021). "For example, the differentiation between asthma, COPD and asthma-COPD overlap encountered in firefighters who cleared debris from WTC relied on measuring eosinophilia and interleukin 4 (IL-4), which increased only in asthma-COPD overlap, and IL-21, which was higher only in isolated asthma and COPD." (PMID 34577834, 2021). "This study aimed to identify the correlation between serum levels of ghrelin, obesity, and asthma with the possible role of some associated inflammatory cytokines—particularly IL-4, IL-5 and IL-21—in children to investigate ghrelin as a future target in the management of asthma." (PMID 32143340, 2020). "Because of IL-21's profound effects in controlling IgE production, supplementation of IL-21 may be useful to rebalance the elevated IgE level in asthma." (PMID 31921177, 2019). "These IL-21-initiated pivotal signaling pathways can be targeted through agonists or antagonists (inhibitors) to modulate T and B cell development and function, and more importantly, intervene and treat multiple immune related diseases, including asthma." (PMID 31921177, 2019). "This dichotomy in the effects of IL-21 in asthma may be due to the timing and location at which IL-21 is preferentially accumulated." (PMID 31921177, 2019). "In addition, the plasma level of IL-21 is significantly elevated in asthma patients in comparison with healthy controls." (PMID 31921177, 2019).
asthma (continued). "Therefore, a thorough understanding of TFH cells and their signature cytokine IL-21 is important to fully elucidate the pathogenesis of asthma." (PMID 31921177, 2019). "It is possible that IL-21 may have multiple roles in asthma, wherein it may sustain germinal center reaction while limiting Ig class-switching toward IgE." (PMID 31921177, 2019). "This role of IL-21, IL-22 and IL-23 cytokines in inflamed lung airways may contribute to the persistence of airway remodelling and hence enhance asthma pathogenesis." (PMID 26772733, 2016). "Also, anti-inflammatory cytokines such as IL-10, IL-12, IL-18, IL-21, IL-23, IL-27 and interferons may have a therapeutic potential in asthma." (PMID 18315837, 2008). "Our findings provide strong evidence that the down-regulation of miRNA-221-5p increased IL-6, IL-17, IL-21 and IL-22 levels, and reduced IL-10, IL-35 and TGF-β levels in vitro model of asthma." (PMID 34863307, 2021). "IL-4, IL-13, and IL-21, which promoted Th2 differentiation and allergic asthma, were also significantly increased in the CD4+ T cells from the asthma mouse model." (PMID 31231429, 2019). "Overall, these observations indicated that OVA DNTs selectively homed in to lung/lung-related tissues and suppressed IL-4, IL-21, and OVA-specific antibody production in an OVA-induced asthma model." (PMID 31534137, 2019). "Moreover, future portable devices equipped with a method to analyze cTFH cells and IL-21 may allow efficient and precise diagnosis of asthma in those who have a family history of the disease or are highly susceptible to severe asthma due to genetic defects and environmental factors." (PMID 31921177, 2019). "Future studies are also required to elucidate the connection between IL-21 and different subsets of TFH cells as well as TFR cells, and to determine how can we use this follicular regulatory network to control asthma disease." (PMID 31921177, 2019). "Thus, IL-21 signalling modulation may be useful for the treatment of asthma." (PMID 18315837, 2008). "This suggests that MICB, PDE4D, and IL‐21 proteins do not influence the occurrence of childhood asthma through BMI." (PMID 38730525, 2024). "This suggests that MICB, PDE4D, and IL‐21 plasma proteins do not influence the occurrence of childhood asthma through BMI." (PMID 38730525, 2024). "There are biomarkers useful for various phenotypes of non-eosinophilic and T2 low asthma; Th17 cells may be responsible for associated with a severe asthma phenotype, which is characterized by neutrophilic inflammation and interleukins such as IL-17A, IL-17F, IL-21 and IL-22." (PMID 40980110, 2023). "The inhibition of FOXP3 attenuated the effects of miRNA-221-5p on the inhibition of IL-6, IL-17, IL-21 and IL-22 levels, and promotion of IL-10, IL-35 and TGF-β levels in in vitro model of asthma following anti-miRNA-221-5p, in comparison with anti-miRNA-221-5p group." (PMID 34863307, 2021). "The inhibition of SOCS1 attenuated the effects of anti-miRNA-221-5p on the increased levels of IL-6, IL-17, IL-21 and IL-22, and suppressed levels of IL-10, IL-35 and TGF-β in in vitro model of asthma following anti-miRNA-221-5p, compared with anti-miRNA-221-5p group." (PMID 34863307, 2021). "The inhibition of RORγt also attenuated the effects of anti-miRNA-221-5p on the increased levels of IL-6, IL-17, IL-21 and IL-22 levels, and inhibited levels of IL-10, IL-35 and TGF-β in in vitro model of asthma following anti-miRNA-221-5p, in comparison with anti-miRNA-221-5p group." (PMID 34863307, 2021). "It is still not very clear why IL-21 signaling plays different roles in asthma; therefore, more studies are needed to provide definitive evidence." (PMID 34867940, 2021). "Modulating IL-21 and TFH cell-regulated IgE production may effectively control asthma development and alleviate inflammatory and hyperresponsiveness symptoms in patients." (PMID 31921177, 2019).
asthma (continued). "The increasing number of studies on TFH cells and IL-21 have inspired numerous possibilities for the development novel immunotherapies to treat asthma." (PMID 31921177, 2019). "We further discuss future therapeutic strategies to treat asthma by targeting TFH cells and IL-21." (PMID 31921177, 2019). "Th17 cells produce some pro-inflammatory cytokines, particularly IL-17A, IL-17F, IL-21, IL-22, TNF-α, and GM-CSF, which may have important roles in the reinforcement of severe form of asthma." (PMID 30116273, 2018). "The expression of miRNA-221-5p was increased in model of asthma, compared with negative group The vitro model of asthma treated with miRNA-221-5p mimic resulted in the reduction of IL-6, IL-17, IL-21 and IL-22 levels, and induction of IL-10, IL-35 and TGF-β levels." (PMID 34863307, 2021). "The role of these cells in human asthma is still unknown, nevertheless, it is of great interest to understand these non-classic TFH cells in the future as targeting on their IL-21 production may ameliorate lung inflammation in asthma." (PMID 31921177, 2019). "However, emerging evidence suggests that T follicular helper (TFH) cells, rather than TH2 cells, predominantly produce IL-4 and IL-21 in B cell follicles and closely regulate IgE class-switching during severe asthma development in both mice and humans." (PMID 31921177, 2019). "In addition, we have discussed the therapeutic strategies for asthma that are based on modulation of TFH cells and IL-21, which may potentially be translated into clinical use in the near future." (PMID 31921177, 2019). "Down-regulation of miRNA-221-5p increased the levels of IL-6, IL-17, IL-21 and IL-22, and reduced those of IL-10, IL-35 and TGF-β in in vitro model of asthma, compared with negative group." (PMID 34863307, 2021). "Although it is still not very clear why IL-21 and IL-21R signaling play different roles in asthma, it will be very exciting to see more studies provide definitive evidence on IL-21's immunomodulating functions in regulating TFH cells, IgE production, and germinal center response in asthma." (PMID 31921177, 2019).
influenza (31 papers, 2012 to 2026). An acute viral infection of the respiratory tract, occurring in isolated cases, in epidemics, or in pandemics; it is caused by serologically different strains of viruses (influenzaviruses) designated A, B, and C, has a 3-day incubation period, and usually lasts for 3 to 10 days. "In any case, these findings provide evidence that both TFH1 ICOS+ and antigen-specific CD4+IL-21+ICOS+CXCR5+ TFH cell subsets are associated with functional antibody responses to influenza vaccination." (PMID 27336786, 2016). "We previously observed that a protective humoral response to the influenza vaccine is associated with increased levels of IL-21 and increased expression of IL-21R in B cells post-vaccination." (PMID 24236161, 2013). "In particular, we demonstrate that an activated state of peripheral T follicular helper cells and decreased vaccine-induced plasma IL-21, the signature cytokine of Tfh, are associated with impaired influenza-vaccine induced antibodies." (PMID 24236161, 2013). "Next, we sorted IL-21lo, IL-21int, and IL-21hi cells from CD45i.v.−CD4+GITR−CD44+ lung cells from influenza-infected IL-21-VFP reporter mice (at 28 dpi)." (PMID 38345472, 2024). "When stimulated with live attenuated influenza vaccine (LAIV) and IL-21, tonsil organoids from both adult and pediatric donors showed an increase in plasmablast frequencyand immunoglobulin G (IgG) production against influenza." (PMID 37339051, 2023). "Several studies show that the induction of ICOS+cTfh or IL-21+ICOS+cTfh cells in blood is correlated with heightened antigen-specific antibody titer or humoral immune responses to influenza vaccination in healthy cohorts or in HIV-1-infected patients." (PMID 35222430, 2022). "In this study, we investigated the impact of IL-21 immunotherapy on antibody response to influenza vaccination in virally suppressed SIV-infected RMs on ART." (PMID 34491910, 2021). "In this study, we show that IL-21 immunotherapy significantly improves influenza vaccine responses in aged SIV+ RMs and point to the potential of IL-21 in vaccinology for special populations." (PMID 34491910, 2021). "The insights gained by this study provide evidence for enhanced influenza vaccine responses with IL-21 immunotherapy in old (average: 21 years, range: 3.8 years) SIV+ ART controlled RMs and potential mechanisms contributing to this effect." (PMID 34491910, 2021). "Taken together, these data demonstrate that IL-21 treatment appears to improve influenza vaccine–induced antibody responses in aged SIV+ animals but not in young SIV+ animals." (PMID 34491910, 2021). "In this study, we demonstrate that an IL-21–based immunomodulatory approach has an adjuvanted effect of improving influenza vaccine–induced antibody responses in SIV+ aged RM." (PMID 34491910, 2021). "Specifically, IL-21 producing pTfh are a strong immunological correlate of T-dependent B cell responses against influenza antigens, as well as HIV and malaria vaccine antigens." (PMID 33868267, 2021). "Herein, we report that the combination of agonistic anti-CD40, IL-4 and IL-21 affords polyclonal B cell stimulation that was comparable to R848 and IL-2 for detection of influenza-specific memory B cells." (PMID 32069813, 2020). "Culturing B cells in the presence of anti-CD40, IL-4 and IL-21 was found to trigger influenza antigen-specific ASC in frequencies similar to R848 and IL-2 stimulation." (PMID 32069813, 2020). "Intriguingly, our data also demonstrate that a small population of IL-10+IL-21+Tfh cells also develop during PR8-influenza." (PMID 30487586, 2018). "We found that cTfh cells at day 7 post-TIV were able to respond to each influenza proteins, and that the specific cTfh cells expressed IL-2, IL-21, and IFN-γ at various levels." (PMID 27231124, 2016).
influenza (continued). "We recently demonstrated that the expansion of peripheral blood influenza-specific CD4+IL-21+ICOS1+ T helper (TH) cells, three weeks after vaccination, associated with and predicted the rise of protective neutralizing antibodies to avian H5N1." (PMID 27336786, 2016). "In ART-treated HIV-infected individuals, responders to the H1N1/09 influenza vaccine had upregulated IL-21 production and increased IL-21 receptor expression on B cells." (PMID 28082992, 2016). "We previously showed that antigen-specific blood CD4+IL-21+ICOS+ TH cells expand three weeks after influenza vaccination." (PMID 27336786, 2016). "For example, experiments using an influenza infection model in IL-21 reporter mice showed that CXCR5+PD-1+IL-21+ Tfh cells can express IFN-γ, IL-10, and T-bet." (PMID 26646149, 2015). "More recently it was demonstrated that TFH-like cells with partial phenotype of GC TFH (ICOS+, PD1+, IL-21+) can be found in the blood of humans after vaccination with MF59-adjuvanted influenza vaccine." (PMID 24755693, 2014). "We have previously shown that the pTfh CD4 T cell subset resides almost exclusively in the memory CD4 T cell pool and that IL-21 production by pTfh is critical for influenza Ab response." (PMID 24236161, 2013). "We previously demonstrated in young HIV+ adults who responded to influenza vaccine that their plasma IL-21 levels increased with upregulation of IL-21R in B cells, while vaccine non-responders failed to do either." (PMID 24236161, 2013). "In a study of vaccine responses to the pandemic H1N1/09 influenza vaccine in HIV infected young patients, impaired vaccine responses were associated with defective function of pTfh and in the IL-21/IL-21R system." (PMID 24236161, 2013). "Similarly, a dysfunctional antigen-specific Tfh cell compartment with an altered IL-21/IL-2 axis has been observed in individuals with impaired influenza vaccine responses." (PMID 39044830, 2024). "Interestingly, we found IL-21 VFP+ TRH cells interacting with B cells in the TLS at 28 days after influenza infection." (PMID 38345472, 2024). "In the case of IL-21, our engineered Q116T variant enhanced the production of flu-specific antibodies while reducing the production of non-specific autoantibodies." (PMID 37339051, 2023). "We and others have demonstrated that compromised influenza vaccine responses in both aging and HIV-infection can be attributed to lower frequencies of antigen-specific pTfh cells, along with a deficiency in IL-21 production by antigen-specific pTfh cells after vaccination." (PMID 34491910, 2021). "Altogether, these studies led us to hypothesize that IL-21 adjuvanted influenza vaccination would induce potent humoral responses in aged SIV+ RMs." (PMID 34491910, 2021). "IL-21 immunotherapy modulates influenza vaccine responses in aged SIV+ RMs." (PMID 34491910, 2021). "Hence, the exploration of IL-21 as a candidate immunomodulatory agent to ameliorate chronic inflammation and improve influenza vaccine responses in aging and HIV/SIV infection is warranted." (PMID 34491910, 2021). "Furthermore, an expansion of AM B cells and concomitant contraction of CD21loCD27– B cells in IL-21–treated animals corresponded with increased antibody titers to flu vaccination." (PMID 34491910, 2021). "Taken together, these data indicate a striking impairment within young and old HIV+ individuals in ICOS and IL-21 induction in Ag.pTfh cells that is not directly associated with magnitude of Ab response following influenza vaccination." (PMID 31100059, 2019). "Importantly, however, our data additionally indicate that the formation of IL-10+IL-21+Tfh cells during influenza appears to be rather transient." (PMID 30487586, 2018). "However, in contrast to chronic LCMV infection, IL-10+IL-21+Tfh cells rapidly declined in influenza-infected hosts." (PMID 30487586, 2018).